FGF21 (fibroblast growth factor 21)
Diseases named in the same sentence as FGF21 in open-access papers (continued):
Sharing a sentence is not in itself a finding about the gene and the disease.
Obesity (continued). "Given that brain FGF21 signaling promotes energy intake and is required for Ucp1 induction, it is possible that these characteristics of mice fed the high-fat KD0P are a result of FGF21 resistance, which has been associated with high-fat diet-induced obesity in mice." (PMID 35433789, 2022). "Whether obesity or adaptation to increasing metabolic stress provokes compensatory upregulation of FGF21, causing FGF21 resistance, is still an open question." (PMID 36034414, 2022). "Several FGF21 analogs are in clinical development for the treatment of obesity associated NAFLD." (PMID 36406708, 2022). "Thus, FGF-21 is believed to be associated with the most prevalent human chronic diseases such as obesity, diabetes and coronary artery diseases." (PMID 35013379, 2022). "Obesity is linked to leptin and insulin resistance, and even though the mechanism and response to pharmacological administration differs, it is not surprising that resistance to another circulating metabolic regulator, FGF21, has been suggested." (PMID 36034414, 2022). "Several studies have shown that serum FGF21 levels may increase in cardiovascular risk factors such as obesity, hypertension and type 2 diabetes." (PMID 35510201, 2022). "Furthermore, miR‐34a has been found to be increased which is associated with obesity and inhibit fat cell browning; Downregulation of miR‐34a can elevate expression of FGF21 and results in induction of the browning genes Ucp1, Pgc‐1, and Prdm16." (PMID 36062491, 2022). "High FGF21 expression and secretion are usually observed in obese mice, but with a concomitant downregulation of its cellular receptors in metabolic tissues, thus leading to the still debated concept that obesity is associated with a resistant state to the endogenous FGF21 action." (PMID 35409319, 2022). "Heightened FGF21 responses to acute sucrose ingestion may be a compensatory mechanism to reduce the metabolic stress associated with obesity or high dietary sugar intake, and these speculations warrant further investigation." (PMID 35491674, 2022). "Moreover, recent studies have shown that circulating levels of FGF-21 are strongly associated with insulin-resistant states such as obesity and type 2 diabetes and inversely associated with both whole-body (muscle) and hepatic insulin sensitivity." (PMID 35883694, 2022). "In preclinical models of obesity and type 2 diabetes, FGF21 could improve glucose homeostasis and promote weight loss." (PMID 35069790, 2022). "Thus, in this context of obesity, the results suggest that deficiency of Mat1a induces the secretion of FGF21 through activation of NRF2." (PMID 35232994, 2022). "In addition, results from correlation and multiple linear regression analysis suggested that high levels of serum FGF21 were associated with age, obesity, and TG, which is in agreement with previously published studies." (PMID 35192641, 2022). "Importantly, high levels of FGF21 have been associated with different metabolic diseases, such as obesity, T2DM, non-alcoholic steatohepatitis (NASH), cardiometabolic disorders, and congenital or acquired lipodystrophy." (PMID 36362103, 2022). "We previously reported that FGF21 is produced by autophagy-deficient hepatocytes as an integrated stress response or ‘mitokine’, which acts as an endocrine hormone and leads to protection against diet-induced obesity and insulin resistance." (PMID 35321438, 2022). "Regarding the inflammatory markers, the chronic inflammatory state in obesity could explain the increased levels of IL-6 and their association with FGF21, as roughly 30% of circulating IL-6 is derived from adipose tissue." (PMID 35207221, 2022). "Thus, FGF21’s beneficial effects on metabolic disorders associated with melanocortin obesity are more pronounced in males." (PMID 34943946, 2021).
Obesity (continued). "Initial studies that observed increased FGF21 levels associated with obesity hypothesized that this reflected a state of “FGF21 resistance”, due to modestly decreased expression levels of both KLB and FGFR1 in perigonadal WAT." (PMID 35046901, 2021). "Indeed, FGF21-analogons administered to patients with obesity and T2D resulted in weight loss, lower low-density lipoprotein cholesterol (LDL-C) and triglycerides (TG), higher high-density lipoprotein cholesterol (HDL-C), but also higher blood pressure." (PMID 33805553, 2021). "recently showed that overexpressing FGF21 from various tissues, including the liver and adipose tissue, rendered mice resistant to high fat diet-induced obesity and associated tissue inflammation and insulin resistance, essentially phenocopying previous FGF21-transgenic mouse studies." (PMID 35046901, 2021). "Mice deficient for whole-body Fgf21 (Fgf21–/–) are more sensitive to diet-induced obesity." (PMID 33411693, 2021). "An association of FGF21- based pharmacotherapy with these glucose- lowering agents to treat multiple obesity- related metabolic complications might constitute a promising strategy that worth further exploration." (PMID 34573919, 2021). "Ay mice develop obesity-associated hyperleptinemia and leptin resistance; partial restoration of leptin sensitivity in FGF21-treated male mice may contribute to lowering blood insulin levels in males." (PMID 34943946, 2021). "Efficient regulation, with large changes in FGF21 secretion in response to the supply of nutrients or nutrient deprivation, is one of the main factors determining the metabolic phenotype less susceptible to the development of obesity and its complications." (PMID 33670024, 2021). "FGF21 is a stress-dependent peptide hormone that is synthesized by several organs, including adipose tissue, and has emerged as a novel therapeutic agent to treat obesity and associated metabolic disorders." (PMID 34192547, 2021). "It is possible, as we suspect that FGF21 levels are induced in response to metabolic stress, that prolonged fasting, obesity, and the severe muscle loss induced by bariatric surgery could all increase circulating FGF21 levels." (PMID 35046901, 2021). "The authors hypothesized that overexpressing KLB from white adipocytes would reduce obesity-associated FGF21 levels, if indeed they were reflective of FGF21 resistance." (PMID 35046901, 2021). "FGF-21 is strongly associated with obesity and T2DM as a regulator of lipid and glucose metabolism." (PMID 33672162, 2021). "Thus, FGF21 administration beneficially affected mice of both sexes despite obesity-associated sex differences in metabolic characteristics, and it induced female-specific activation of gene expression in WAT." (PMID 34638898, 2021). "Here, we found that FGF21 is a critical hepatokine in Th2 cytokine-mediated immunoregulatory responses, which may ameliorate metabolic impairments caused by obesity and insulin resistance." (PMID 34073755, 2021). "Therefore, expanding knowledge of the epigenetic basis associated with blunted FGF21 response to diet, is important for identifying individuals at risk and preventing the metabolic complications of obesity." (PMID 33670024, 2021). "Thus, it has now been proposed that obesity-associated FGF21 is increased as a compensatory mechanism to preserve insulin sensitivity." (PMID 32158768, 2020). "Importantly, obesity is associated with FGF21 resistance in peripheral tissue and the CNS due to reduced FGF21 receptor expression." (PMID 32423100, 2020). "It has been proposed that obesity-associated increased FGF21 levels reflect a “spill-over” from cells that are experiencing metabolic stress; however, this hypothesis does not explain the further increased FGF21 levels that accompany RYGB." (PMID 32158768, 2020).
Obesity (continued). "However, we corrected the analysis for false positives, as well as there are several previous studies linking FGF-21 with obesity and diet, thus we believe the association observed in our study is not a random finding." (PMID 32404980, 2020). "However, recent evidence has paradoxically suggested an association between serum FGF21 levels and obesity-associated metabolic syndrome." (PMID 32158768, 2020). "Interestingly, NAFLD and obesity are related to an increase in serum FGF21, and weight loss leads to its reduction in both mice and men." (PMID 32708435, 2020). "BDNF and FGF21 have been implicated in the pathogenesis of obesity, T2DM, and metabolic diseases." (PMID 32210348, 2020). "In this context, the restoring of FGF21 signaling can be considered as a potential therapeutic strategy to improve the metabolic parameters of obese individuals and to reduce the risk of obesity-related diseases and some evidence support this hypothesis." (PMID 31480627, 2019). "FGF21 levels might be helpful in prediction of the risk of cardiometabolic comorbidities development especially in patients with severe psoriasis and obesity." (PMID 31847236, 2019). "This indicated that FGF21 deficiency augmented obesity-induced skeletal muscle inflammation and hence may exaggerate the ubiquitin-proteasome pathway, which is activated by the inflammatory signal, leading to increased protein degradation." (PMID 31312114, 2019). "This long-term randomised control trial in healthy overweight or obese individuals is adding to the growing literature investigating the role that FGF-21 may have in obesity and associated weight loss." (PMID 31817052, 2019). "Moreover, the beneficial effects of FGF21 on obesity-associated metabolic disorders are dependent on the increase of adiponectin mRNA and protein and are obliterated in adiponectin-deficient mice." (PMID 30374109, 2018). "Reduced DNA methylation is associated with enhanced induction of hepatic FGF21 expression after PPARα activation, which may partly explain the attenuation of diet-induced obesity in adulthood." (PMID 29434210, 2018). "Central FGF21 resistance may be among the overlooked underlying pathologies contributing to aberrant dietary choices that exacerbate obesity and diabetes." (PMID 30389922, 2018). "Having observed the profound effects on body weight exerted by FGF21 gene transfer to the liver, and taking into account that obesity and T2D are pathologies associated with aging, we set out another study in which animals began HFD feeding when older, at the age of 29 weeks (“adults”)." (PMID 29987000, 2018). "Fgf21 has been implicated in control of numerous lipid/obesity-related liver pathologies." (PMID 29351395, 2018). "Previous studies have demonstrated that FGF-21 levels are increased in association with obesity and hepatic steatosis either because of unfavorable lipid and glucose metabolism associated with these conditions, or because these conditions are associated with FGF-21-resistance." (PMID 27182456, 2016). "Increased serum FGF21 concentration may also be a compensatory response to comorbid metabolic diseases that caused HFpHF, such as diabetes and obesity, which caused massive secretion of FGF21 from liver and adipose tissue." (PMID 27650781, 2016). "A SNP located in the exon of FGF21 is significantly associated with the percentage of total caloric intake from protein and carbohydrates, indicating that FGF21 is a potential susceptibility gene for obesity and diabetes." (PMID 26483756, 2015). "Understanding the direct function of FGF21 on liver is complicated since most studies have focused on NAFLD in the context of obesity and pharmacologic doses of FGF21 induce rapid weight loss, making it difficult to identify the primary effects of FGF21 on liver metabolism." (PMID 26594197, 2015).
Obesity (continued). "Interestingly, the effects of LY2405319 (LY), an engineered FGF21 variant, in a randomized, placebo-controlled, double-blind proof-of-concept trial on 46 patients with obesity and type 2 diabetes has been recently reported." (PMID 25295245, 2014). "Recently, genetic association studies in humans demonstrated that common polymorphisms in the Fgf21 signaling pathways were associated with metabolic risks and syndromes, such as high cholesterol and body mass risks, obesity and diabetes and even dietary macronutrient intake." (PMID 24587261, 2014). "Notably, the hepatokine/adipokine FGF21, circulating levels of which are elevated in obesity and type 2 diabetes, has been implicated as a key metabolic regulator." (PMID 24498293, 2014). "A single nucleotide polymorphism (SNP) in the Fgf21 exon was correlated with the percentage of total caloric intake from protein and carbohydrate, suggesting that FGF21 is a potentially susceptible gene for obesity and diabetes." (PMID 25071723, 2014). "Autophagy-deficient mice have up-regulated FGF-21 levels, increased beta-oxidation in muscle and adipose tissue, reduced fat mass, heightened insulin sensitivity, and they are spared from diet-induced obesity and hepatosteatosis." (PMID 23840612, 2013). "The activation of adipose tissue by FGF21 through FGFR1 was suggested by genetic deletion of FGFR1 in adipocytes in mice used in the current study, and this tissue- and molecule-specific actions of FGF21 underlies the breadth of its in vivo beneficial effects on treatment of obesity and diabetes a." (PMID 23106963, 2012). "This gives us a speculative clue that may suggest that the mechanism of increased FGF-21 levels in cardiovascular disease is similar to obesity-associated resistance to insulin." (PMID 21206918, 2010). "However, this does not mean that FGF21 is not helpful for diabetes and insulin resistance in humans, and FGF21 analogs can improve the insulin signaling pathway by improving lipid metabolism and reducing lipotoxicity and chronic inflammation associated with obesity in humans." (PMID 40881124, 2025). "Our findings indicate that sustained and chronic HFD-induced stress, especially in aged animals, could ultimately disrupt the compensatory transcriptional mechanisms regulating FGF21, reducing signaling efficiency and potentially accelerating obesity- and aging-associated fatty liver progression." (PMID 40585885, 2025). "In addition, an increased plasma FGF21 concentration in patients treated with dialysis may also be associated with concomitant chronic inflammation, insulin resistance, or obesity." (PMID 39064306, 2024). "In obese mice, FGF21 treatment has been shown to notably enhance insulin sensitivity, promote energy expenditure, and augment fat oxidation while also inhibiting de novo lipogenesis in the liver, thereby ameliorating obesity and its associated metabolic complications." (PMID 38673797, 2024). "Indeed, increased serum FGF-21 levels have been associated with diabetes, obesity, and MetS." (PMID 38222178, 2023). "In contrast, endogenous FGF21 increased energy expenditure in the setting of low protein, high-energy intake, contributing to weight loss, and FGF21 overexpression or pharmacological administration of FGF21 had similar effects in the context of obesity or diabetes." (PMID 37537627, 2023). "Fibroblast growth factor 21 (FGF-21), a new endocrine hormone with the regulatory effects on energy homeostasis and metabolism of lipid and glucose, has been known to inhibit the inflammation and cell damage caused by oxidative stress in obesity and insulin-resistant states including NAFLD." (PMID 35745238, 2022). "Obesity is associated with elevated levels of cFGF21, and the expected beneficial effects of FGF21 for improving glucose tolerance and reducing plasma glucose and triglyceride levels are attenuated or even lost in obesity, suggesting the existence of an FGF21-resistant state." (PMID 36093108, 2022).
Obesity (continued). "Moreover, serum FGF21 levels were also associated with aging and obesity, even in T1DM patients." (PMID 35192641, 2022). "Thus, the present findings suggest that individuals with overweight and obesity might have altered FGF21-linked neural signaling in these brain regions implicated in food intake regulation, but future work is needed to test causal mechanisms." (PMID 35491674, 2022). "Hence, FGF21 could be considered a potential diagnostic biomarker and therapeutic agent for metabolic diseases such as obesity, type 2 diabetes mellitus (T2DM), and fatty liver." (PMID 36457562, 2022). "However, FGF21 is strongly related to obesity, and we have observed that, when stratified for BMI, T2D patients and healthy controls have the same level of FGF21, suggesting that the reported association of FGF21 with T2D is likely mediated by BMI." (PMID 33131010, 2021). "However, whether FGF21 resistance exists, and whether it explains the obesity-associated rise in circulating FGF21 levels is still under debate." (PMID 35046901, 2021). "FGF21 may represent a promising next-generation preventive and therapeutic strategy that warrants comprehensive testing in human clinical trials of obesity-associated pancreatic cancer, pancreatitis, and other inflammation-related disease states such as NASH and hepatocellular cancer." (PMID 33668583, 2021). "We hypothesized that FGF21 protein levels are associated with metabolic abnormalities, placing special attention to the alterations in relation to the concurrence of overweight/obesity in people living with HIV (PLWH)." (PMID 34019585, 2021). "To the best of our knowledge, for the first time, we demonstrated that obesity-related circulating exosomes can impair insulin signaling pathways and associated components, as well as increase intracellular TG content, and decrease the secretion of FGF21 in the hepatocytes." (PMID 32322309, 2020). "Interestingly, FGF21 has recently been shown to have both antihypertrophic and cardioprotective actions, and has been considered as a promising new therapy target obesity and associated diseases, by activating BAT and by acting on WAT and the liver." (PMID 33050331, 2020). "Thus, we thought that the protective action of FGF21 against obesity-induced atrophic responses may be associated with its anti-inflammatory action." (PMID 31312114, 2019). "Therefore, induction of FGF21 expression could be a candidate therapeutic regiment for the treatment of obesity and its associated metabolic disorders." (PMID 28466020, 2017). "In fact, the hormonal factor FGF21 is emerging as a key regulator of metabolism in general, providing significant health benefits and protective effects against metabolic disorders associated with obesity, such as insulin resistance, type II diabetes, and dyslipidemias." (PMID 26379627, 2015). "Thus, obesity is also linked to a FGF21- resistant condition." (PMID 24189525, 2013). "Overall, FGF21 has a multifaceted and crucial role in metabolism regulation, with its effects dysregulated in metabolic disorders such as diabetes and obesity, pointing to FGF21 as a potential new candidate to modulate cancer metabolism." (PMID 41131959, 2026). "Although fibroblast growth factor 21 (FGF21) and its co‐receptor, Klotho, are implicated in mediating DPR benefits, diet‐induced obesity by HF appears to blunt their response." (PMID 41549510, 2026). "Impaired FGFR1/β-Klotho signaling, as observed in obesity, diminishes FGF21 responsiveness, whereas pharmacological activation of this pathway restores thermogenic capacity through UCP1 induction." (PMID 41596403, 2026). "Previous studies have shown that circulating FGF21 levels are elevated in obese mice fed a high-fat or high-carbohydrate diet, suggesting the development of FGF21 resistance during the onset of obesity." (PMID 41470800, 2025).